FOXM1 (forkhead box M1)
Diseases named in the same sentence as FOXM1 in open-access papers (continued):
Sharing a sentence is not in itself a finding about the gene and the disease.
breast cancer (continued). "Our results suggest that FoxM1 may be a potential therapeutic target for the treatment of aggressive breast cancers." (PMID 29707121, 2018). "FOXM1 also mediated resistance to herceptin and paclitaxel in breast cancer." (PMID 29435149, 2018). "We found the FOXM1 associated pathway is the top Yin upregulated pathway in TNBC but not in other subgroups of breast cancers." (PMID 29301506, 2018). "Increased expression of FOXM1 is observed in a variety of human cancers, such as ovarian cancer, breast cancer, prostate cancer, hepatoma, angiosarcoma, colorectal cancer, melanoma, lung cancer, and gastric cancer, which is consistent with the results obtained from the TCGA database." (PMID 30208972, 2018). "In addition, overexpression of FOXM1 reduces the sensitivity of HER2-positive breast cancer cells to lapatinib, while inhibition of FOXM1 rescues resistance to lapatinib resistance." (PMID 29180117, 2018). "In ERα-positive breast cancer cells, ERα can upregulate FOXM1 expression by binding to the ERE." (PMID 30208972, 2018). "FOXM1 was reported to confer resistance to herceptin and paclitaxel by altering microtubule dynamics to protect tumor cells from paclitaxel-induced apoptosis in breast cancer." (PMID 29435149, 2018). "We examined the YMR score of the FOXM1 and PPARα pathways in breast cancer cell lines." (PMID 29301506, 2018). "Silence of NF-κB reduced the expression of FOXM1 in breast cancer cells." (PMID 29472532, 2018). "Moreover, the expression of both FOXM1 and UBE2C in breast cancer has already been associated with ErbB2 pathway." (PMID 29596365, 2018). "Similarly, basal-like breast cancers are also driven by FOXM1 which also indicates that growth inducing cascades can be targeted for basal-like breast cancer." (PMID 30558195, 2018). "Similarly, FOXM1 overexpression has also been demonstrated to confer acquired cisplatin resistance in breast cancer cells." (PMID 29180117, 2018). "Likewise, another screening also identified a small molecule FDI-6 as a potent FoxM1 inhibitor in breast cancer cells." (PMID 29765517, 2018). "Consistently, FOXM1 depletion can sensitize breast cancer to paclitaxel-induced senescence." (PMID 29180117, 2018). "Given that YAP induces FOXM1 in our cell lines, and that FOXM1 has been proposed to be a therapeutic target in breast cancer, we next sought to assess whether FOXM1 inhibition induces CCA cell death." (PMID 29464042, 2018). "However, perspectives on the function of FoxM1 in breast cancer (BC) remain conflicting, and mostly were from basic research." (PMID 29416660, 2018). "Moreover, FoxM1 was reported as a master regulator and a biomarker in breast cancer by multiple studies." (PMID 28950860, 2017). "In addition, we treated MDA-MB-436 breast cancer cells with M-FOXM1 Apt and measured the levels of FOXM1, Cdc25B, and Cyclin B1." (PMID 28358012, 2017). "Both knocking down of AURKA and FOXM1 could reduce tumour initiation ability of breast cancer cells." (PMID 28114286, 2017). "Depletion of FOXM1 resensitized breast cancer cells to epirubicin-induced cellular senescence." (PMID 28051999, 2017). "In breast cancer cells FOXM1 expression conferred cisplatin resistance." (PMID 29228593, 2017). "Also, overexpression of miR-802 suppresses breast cancer cell proliferation by downregulating FOXM1." (PMID 27999212, 2017). "The impact of FoxM1 in breast cancer progression is widely demonstrated." (PMID 28770020, 2017). "Finally, at the level of regulation activity, we applied the Binding Association with Sorted Expression (BASE) algorithm to a primary breast cancer expression dataset to infer FOXM1 regulatory activity in patient samples based on its target gene expression." (PMID 29100329, 2017). "Another study proved a positive correlation between HER2 status and FoxM1 expression in breast cancer tissue compared to normal breast counterpart, suggesting that FoxM1 is a downstream target of HER2 and could be used as a marker of HER2 overexpression." (PMID 28770020, 2017).
breast cancer (continued). "Indeed, FOXM1 and ERα co-bind DNA in breast cancer cells and modulate the expression of specific genes." (PMID 28666461, 2017). "In accordance with the pivotal role of FOXM1 in cancer, its inhibition suppressed cell proliferation and tumor growth of breast cancer and promoted the cytotoxic effects of platinum compounds, doxorubicin hydrochloride and olaparib in epithelial ovarian cancer." (PMID 29228593, 2017). "We also discovered that SLPI physically interacts with the retinoblastoma tumor suppressor protein (Rb) and releases FoxM1 from the Rb-FoxM1 complex, which may activate FoxM1 target genes involved in breast cancer metastasis." (PMID 29312532, 2017). "FOXM1 is a known prognosis marker in breast cancer, and we show it is the relative gene activities in the transcriptome of ER-negative breast cancer that determine its role in breast cancer pathogenesis and prognosis." (PMID 26975659, 2016). "Overall, these results suggest that FOXM1 is involved in eEF2K expression in breast cancer cells." (PMID 26918606, 2016). "Thus, they showed that FOXM1 is one of the primary cellular targets of thiostrepton in breast cancer cells." (PMID 27454576, 2016). "Additionally, their work verified the overexpression of FOXM1 in breast cancer on both the RNA and protein level." (PMID 26942015, 2016). "Moreover, coexpression of FOXM1, survivin, and nuclear XIAP was associated with poor outcomes of women with stage III breast cancer with significantly reduced 5- and 10-year survival rates versus women with tumors without these features." (PMID 26942015, 2016). "Because FOXM1 is also involved in these functions in breast cancer cells, we hypothesized that FOXM1 may transcriptionally regulate eEF2K expression." (PMID 26918606, 2016). "Kaplan-Meier curve analysis showed patients with FOXM1 expression above the median had significantly poorer survival compared to those with FOXM1 expression below the median, both in breast cancer (1115 patients, p=2.7e-07) and lung cancer (1210 patients, p=3.2e-11)." (PMID 27764801, 2016). "In here, we show that FOXM1 depletion can sensitize breast cancer cells and mouse embryonic fibroblasts into entering paclitaxel-induced senescence, with the loss of clonogenic ability, and the induction of senescence-associated β-galactosidase activity and flat cell morphology." (PMID 25961928, 2016). "It has been shown that FoxM1 is highly expressed in breast cancer." (PMID 26905733, 2016). "Herein, we describe some breast cancer therapeutic strategies targeting FOXM1." (PMID 26942015, 2016). "The effect of FOXM1 on biology of breast cancer was evaluated in 236 women with breast cancer." (PMID 26942015, 2016). "Taking into consideration the significant role of FOXM1 in breast cancer biology this transcription factor could become an attractive target for cancer treatment." (PMID 26942015, 2016). "The correlation between FOXM1 and ER+ breast cancer has also been shown on the genetic level." (PMID 26942015, 2016). "FOXM1 was found to contribute to cisplatin (a platinum agent) resistance in breast cancer cells." (PMID 26942015, 2016). "Given that OTUB1 is a deubiquitinating enzyme that removes polyubiquitin chains and promotes stability of target proteins, these data suggest that OTUB1 binds to FOXM1 and modulates its ubiquitination and degradation in response to genotoxic treatment in breast cancer." (PMID 26148240, 2016). "The high levels of RNF8 and low levels of RNF168 in steady-state untreated MCF-7 breast cancer cells may also explain the inability of RNF8 overexpression or its depletion to modulate FOXM1 expression." (PMID 27526106, 2016). "We further found that forced expression of miR-671-5p in breast cancer cell lines resulted in FOXM1 down-regulation and significant proliferation and invasion inhibition, which implicates a tumor suppressor function of miR-671-5p by targeting FOXM1." (PMID 26588055, 2016).
breast cancer (continued). "We propose that this type of DC-based immunotherapy may be applicable to breast carcinoma, pulmonary cancer, and other types of tumors expressing FoxM1." (PMID 27351282, 2016). "Therefore, our findings elucidate a hitherto unexplored mechanism for FoxM1 in breast cancer progression." (PMID 25869208, 2015). "Moreover, we also found that the PDGF/AKT pathway activates FoxM1 expression in breast cancer cells." (PMID 25869208, 2015). "Thus, FOXM1 has potentially acquired new tissue/cell type specific functions in OAC in keeping with the novel recently identified roles of FOXM1 in gliomas, breast cancer and lymphoblastomas through targeting different gene networks in each tumour type." (PMID 25889361, 2015). "Indeed, FOXM1 is recruited to DNA in lymphoblastoid cells by NF-kB and FOXM1 co-operates with ERα in driving gene expression in the context of breast cancer." (PMID 25889361, 2015). "Moreover, FoxM1 activates the PDGF/PDGFR pathway in breast cancer cells by stimulating the transcription of PDGF-A." (PMID 25869208, 2015). "Likewise, knockdown of FoxM1 also significantly inhibited tumorigenesis in human breast cancer MDA-MB-231 cells." (PMID 25869208, 2015). "Further, B-MYB and FOXM1 target genes, such as CCNB1 and AURKA, are associated with breast cancer." (PMID 25909288, 2015). "As such, the new FOXM1 protein targets that we identified in MCF7-FOXM1 cells may be especially relevant for improving human breast cancer diagnosis and therapy." (PMID 26087310, 2015). "To determine whether our findings have clinical relevance in human breast cancer, we investigated the expression of FoxM1, PDGF-A, and phospho-AKT in human breast tumor samples." (PMID 25869208, 2015). "Therefore, our findings elucidate a novel FoxM1/PDGF/AKT regulatory feedback loop that promotes breast cancer cell growth and tumorigenesis." (PMID 25869208, 2015). "Importantly, these FOXM1 target proteins were also transcriptionally up-regulated in patient samples in vivo, in human breast cancer epithelial cells isolated by laser-capture micro-dissection, highlighting their clinical relevance." (PMID 26087310, 2015). "For instance, it has been shown that deregulated FOXM1 expression can confer resistance to chemotherapeutic drugs, such as cisplatin and epirubicin, and protect cancer cells against DNA-damage induced cell death in breast cancer." (PMID 24824601, 2014). "FoxM1 is a physiological regulator of ERα expression in breast cancer cells." (PMID 25522167, 2014). "In cultured cells, FOXM1 promoted breast cancer aggressiveness and therapy resistance which could be reversed by FOXM1 inhibition or knockdown." (PMID 25213081, 2014). "We analyzed FOXM1 protein expression by immunohistochemistry in 501 ER-positive breast cancers." (PMID 25213081, 2014). "Genes within 20 kb of binding sites belonging to cluster C1 and whose expression was impacted by FOXM1 knockdown were used to generate a gene predictor that was employed to interrogate two large, independent data sets of ERα-positive breast cancer patients treated with TAM." (PMID 25213081, 2014). "Because proteasome inhibitors are already used in the clinic to treat multiple myeloma, it is possible that these inhibitors might prove being beneficial in breast cancers patients, whose tumors highly express FOXM1." (PMID 24342878, 2013). "Interestingly, PD0332991 is currently tested in clinical trials (phase II) in breast cancer patients emphasizing the importance of FOXM1 in breast cancer." (PMID 24342878, 2013). "Thiostrepton, a natural product with antibiotic properties isolated from Streptomyces azureus, is known to inhibit the binding of FoxM1 to genomic target sites and cellular studies showed that thiostrepton selectively targets breast cancer cells by inhibiting FoxM1 expression." (PMID 23857410, 2013). "Furthermore, emerging studies have shown that FOXM1 confers resistance to a wide variety of breast cancer chemotherapeutic drugs." (PMID 23087907, 2012).
breast cancer (continued). "Additionally, using RT-PCR, FOXM1 was found to be overexpressed in breast cancer in comparison to normal breast tissue both on the RNA and protein level." (PMID 21314937, 2011). "Consistently, FOXM1 expression is specifically elevated in breast carcinomas." (PMID 21314937, 2011). "Taken together, our analyses showed FOXM1 overexpression in human breast carcinoma relative to normal breast tissue on RNA and protein level indicating that FOXM1 may represent a novel oncogene in human breast cancer development." (PMID 18254960, 2008). "FOXM1 may represent a novel breast tumour marker with prognostic significance that could be included into multi-marker panels for breast cancer." (PMID 18254960, 2008). "Interestingly upregulation of FOXM1 was highly abundant in the breast cancer cell line MDA-MB231, a cell line which was shown to be strongly metastatic in nude mouse models." (PMID 18254960, 2008). "FOXM1 may represent a novel breast tumour marker with prognostic significance that could be included into multi-marker panels for breast cancer detection and treatment." (PMID 18254960, 2008). "In the present study we systematically analysed the expression of FOXM1 in human breast carcinomas and normal breast tissue on both the mRNA and protein level and analysed the results especially in correlation to hormone receptor status, HER2 status and patient survival data." (PMID 18254960, 2008). "Despite these limitations, we observed significant changes in the expression of the oncogenic transcription factor Foxm1 and glucose transporter Glut1, which are observed in a significant number of breast cancers and have not been previously linked to dietary changes." (PMID 40713647, 2025). "Additionally, FOXM1, an oncogenic transcription factor highly expressed in various cancers—including skin, colon, and breast cancers—induces EMT by modulating key molecules such as cyclin B1, Slug, and Snail, thereby promoting tumor cell proliferation and migration." (PMID 40186131, 2025). "Consequently, AURKA and FOXM1 collaboratively contribute to the aggravation of breast cancer." (PMID 40003882, 2025). "Vast majority of research on FOXM1 consistently highlights its high expression correlating with radio and chemoresistance, which may lead to unfavorable patient outcomes in various cancers such as breast cancer, small cell lung cancer." (PMID 40561071, 2025). "Collectively this suggests the AKT-FOXO3-FOXM1 axis plays a pivotal role in response to AKTi in ER+ breast cancer with PIK3CA mutations with and without expression of PTEN, that FOXO3 expression loss can mediate resistance, and that FOXM1 downregulation is a potential biomarker of response." (PMID 40263319, 2025). "Additionally, FOXM1 was reported to activate Wnt/β-catenin signaling pathway in breast cancer, thus promoted proliferation, invasion and epithelial-mesenchymal transition of breast cancer cells." (PMID 38978058, 2024). "Therefore, we suggested that CDCA5 promoted progression of breast cancer via CDCA5/FOXM1/Wnt axis for the first time, CDCA5 may serve as a novel therapeutic target for breast cancer treatment." (PMID 38978058, 2024). "Consequently, Rabeprazole and Pantoprazole are potential novel inhibitors of FOXM1 and may be used as FOXM1-targeted cancer therapy in treatment of breast cancer and other FOXM1-driven cancers." (PMID 38918225, 2024). "Accordingly, the knockdown of FOXM1 or its downstream targets was found very effective in restoring standard chemotherapy sensitivity in many human cancers, including colorectal cancer, Lung carcinoma, breast cancer, ovarian cancer, prostate cancer, esophageal cancer." (PMID 38697979, 2024). "Moreover, VEGF has also been demonstrated to be a direct target of FOXM1 in breast cancer cells." (PMID 38338955, 2024). "For example, YTHDF1 accelerates FOXM1 translation and drives breast cancer (BC) metastasis through m6a modification." (PMID 39060874, 2024).
breast cancer (continued). "Therefore, we showed that Wnt/β-catenin signaling may serve as the possible downstream of FOXM1 in breast cancer progression." (PMID 38978058, 2024). "Our data collectively documented that USP22 maintain breast cancer stemness in part through stabilizing ITGB1 transcription factor FoxM1 to promote breast cancer growth and metastasis, which define a previously unknown USP22-FoxM1-ITGB1 pathway in breast cancer pathogenesis." (PMID 37398311, 2023). "Notably, OGT’s nutrient sensing role has been previously linked with breast cancer tumorigenesis via the transcription factor FoxM1, but since FoxM1 is not an OGT substrate there remains a missing link in this connection." (PMID 37231419, 2023). "Hence, understanding the molecular mechanisms of FOXM1 regulation could shed light on new avenues for breast cancer diagnosis and therapeutics." (PMID 37025658, 2023). "Importantly, FOXM1 acts as both a transcriptional activator and a repressor, with the latter activity recently shown to support metastatic progression in a model of luminal B breast cancer." (PMID 36795481, 2023). "Additionally, FOXM1 has been identified as promoting therapeutic resistance in multiple treatment modalities across various cancers, including pancreatic, glioblastoma, and breast cancers." (PMID 37174744, 2023). "Furthermore, FOXM1 is a well-known transcription factor that is upregulated and overexpressed in aggressive phenotypes and has a poor prognosis in most human cancers as well as breast cancer." (PMID 36077657, 2022). "In addition, FOXM1 and ER-α were closely related in breast cancer." (PMID 35615146, 2022). "In addition, FOXM1 facilitates breast cancer cell stemness and migration." (PMID 35039475, 2022). "Thus, mechanisms that lead to only a partial loss or altered functionality of the LATS proteins might be required to abrogate the RASSF1A-mediated suppression of YAP1, ERα and FOXM1, thereby fostering the initiation and progression of luminal breast cancer." (PMID 34831091, 2021). "To investigate whether LATS1 and/or LATS2 are indeed responsible for RASSF1A-mediated suppression of YAP1, ERα and FOXM1 expression in ERα+ breast cancer cells, we employed stable knockdown of either LATS1, LATS2 or LATS1+LATS2 in RASSF1A-conditional MCF7 cells." (PMID 34831091, 2021). "Moreover, a meta-analysis showed that a downsized four-gene signature, consisting of DDX19A, FOXM1, KPNA4, and H2AFV, represents a highly significant finding for the biology underlying histological grades in breast cancer, in particular, regarding cell proliferation, and DNA stability." (PMID 33968728, 2021). "In addition, our results also show that FOXM1 is specifically upregulated in Basal-subtype, and whether BUB1 depends on FOXM1 to play roles requires further exploration in Basal-subtype breast cancer." (PMID 33644115, 2021). "Thus, their interaction with cancer related axes including FOXM1/GATA3/FOXA1/ESR1 axis might affect the course of breast cancer." (PMID 34094972, 2021). "Likewise, imipramine blue could suppress breast cancer growth and metastasis by inhibiting FoxM1-mediated DNA repair processes." (PMID 33407221, 2021). "Furthermore, we observed the pharmacological inhibition of YAP1 phenocopies RASSF1A-mediated suppression of ERα and FOXM1 expression, suggesting that drugs that target YAP1 might compensate for the loss of RASSF1A function in ER+ breast cancer cells." (PMID 34831091, 2021). "Hence, future studies could be directed towards using these inhibitory compounds in a syngeneic model of metastatic breast cancer to investigate the role of FOXM1 in mobilizing immune cells to facilitate metastatic progression." (PMID 32961773, 2020).